RAB24 (RAB24, member RAS oncogene family)
Description:
The small GTPases Rab are key regulators of intracellular membrane trafficking, from the formation of transport vesicles to their fusion with membranes. Rabs cycle between an inactive GDP-bound form and an active GTP-bound form that is able to recruit to membranes different sets of downstream effectors directly responsible for vesicle formation, movement, tethering and fusion. RAB24 is an atypical RAB protein that presents low GTPase activity and thereby exists predominantly in the GTP-bound active state. RAB24 is required for the clearance of late autophagic vacuoles under basal conditions. It is not needed for starvation-induced autophagy. Involved in the modulation of meiotic apparatus assembly and meiotic progression during oocyte maturation, possibly through regulation of kinetochore-microtubule interaction.
Tractability: Antibody: its Gene Ontology location is reachable by antibodies, with high confidence. PROTAC: ubiquitination databases record sites on it; its protein half-life has been measured.
Gene: Protein-coding gene on chromosome 5 (177,301,198 to 177,303,744, reverse strand). Ensembl gene ENSG00000169228.
Subcellular location: Cytoplasm, cytosol; Membrane; Cytoplasmic vesicle, autophagosome membrane; Cytoplasm, perinuclear region; Cytoplasm, cytoskeleton, spindle
Subcellular location (Human Protein Atlas): Cytosol
Pathways (Reactome):
Immune System: Neutrophil degranulation
Metabolism of proteins: RAB geranylgeranylation
Gene Ontology:
Molecular function: protein binding; G protein activity; GTPase activity; GTP binding
Biological process: attachment of spindle microtubules to kinetochore; autophagy; meiotic nuclear division; oocyte maturation
Cellular component: cytosol; membrane; mitochondrion; autophagosome; autophagosome membrane; endocytic vesicle; perinuclear region of cytoplasm; plasma membrane; secretory granule membrane; bounding membrane of organelle; cytoplasm; spindle
Genetic constraint (gnomAD): Loss-of-function variants: 8 observed, 33 expected, observed/expected ratio (o/e) 0.24, 90% interval 0.14 to 0.44. The upper end of that interval is the gene's LOEUF score, 0.44, which puts it in group 1 of 6, group 1 being the genes least tolerant of losing a copy. Missense variants: 193 observed, 279.72 expected, observed/expected ratio (o/e) 0.69, 90% interval 0.61 to 0.78. Synonymous variants: 106 observed, 101.02 expected, observed/expected ratio (o/e) 1.05, 90% interval 0.9 to 1.23.
Homologues: Orthologues: chimpanzee RAB24 (100% identical), macaque RAB24 (100% identical), dog RAB24 (99% identical), mouse Rab24 (99% identical), guinea pig RAB24 (97% identical), rabbit RAB24 (90% identical), rat Rab24 (90% identical), tropical clawed frog rab24 (80% identical), zebrafish rab24 (76% identical). Paralogues in human: RAB5C (36% identical), RAB5A (35% identical), RAB5B (35% identical), RAB22A (33% identical), RAB36 (32% identical), RAB17 (31% identical), RAB21 (31% identical), RAB31 (31% identical), RAB6B (31% identical), RAB6A (30% identical), RAB11A (29% identical), RAB11B (29% identical), and 56 more.
Diseases named in the same sentence as RAB24 in open-access papers:
RAB24 is named in the same sentence as 29 diseases in open-access papers, as found by Europe PMC text mining. Sharing a sentence is not in itself a finding about the gene and the disease. The quoted sentences say what the papers report.
Ataxia (6 papers, 2014 to 2025). Ataxia refers to impaired coordination of voluntary muscle movement. "Another missense variant in RAB24, p.Glu38Pro, was previously reported to cause a clinically similar form of cerebellar ataxia in Gordon Setters and Old English Sheepdogs." (PMID 40869982, 2025). "A missense mutation in exon 1 of the autophagy-linked GTPase (RAB24) gene is known to cause a later-onset form of cerebellar ataxia in Old English sheepdogs and Gordon setters." (PMID 36292596, 2022). "Furthermore, a recent study reported corresponding histological findings in dogs with a juvenile-onset progressive cerebellar ataxia, caused by a recessive mutation in the autophagy-linked RAB24 gene." (PMID 25875846, 2015). "For example, a polymorphism in the Ras-Related Protein Rab-24 (RAB24) gene, a member of the RAS oncogene family, which encodes a protein necessary for autophagosome trafficking, was found responsible for juvenile onset ataxia in some breeds." (PMID 31681409, 2019). "However, the atypical RAB protein RAB24 is relevant to the transportation of autophagic vacuoles, autophagy–lysosomes, and the clearance of autophagosomes in the late period, and it is involved in ataxia, cancer, etc.." (PMID 35645767, 2022).
colon cancer (3 papers, 2021 to 2023). "TTP family mRNA levels (ZFP36, ZFP36L1 and ZFP36L2 mRNAs) were generally decreased and TTP-targeted cytokine mRNA levels (TNF, COX2, PPARR and RAB24 mRNAs) were relatively high in the colon cancer cells." (PMID 33723275, 2021).
hepatocellular carcinoma (3 papers, 2017 to 2022). A malignant tumor that arises from hepatocytes. "Furthermore, RAB24 protein was reported to promote malignant phenotype transformation in hepatocellular carcinoma." (PMID 33178587, 2020). "In studies in tumors, RAB24 was identified as a direct target of miR-615-5p in hepatocellular carcinoma (HCC)." (PMID 35488119, 2022).
hereditary ataxia (2 papers, 2014 to 2025). An instance of an atactic disorder that is caused by an inherited genomic modification in an individual. "We identified a mutation in RAB24, a gene associated with autophagy, in Old English Sheepdogs and Gordon Setters with hereditary ataxia." (PMID 24516392, 2014). "RAB24 should be considered a candidate gene for unexplained forms of hereditary ataxia in human patients." (PMID 40869982, 2025).
male infertility (2 papers, 2019 to 2023). The inability of the male to effect fertilization of an ovum after a specified period of unprotected intercourse. "This can potentially lead to the pathogenesis of male infertility, as RAB-24 is an autophagy-related gene, and its differential expression can affect the initiation as well as the progression of spermatogenesis." (PMID 37509082, 2023). "In our study, we found that putative target genes of hsa-miR-372-3p included autophagy relative gene such as RAB-24 Increasing evidence suggests that autophagy play a critical role in the pathogenesis of male infertility." (PMID 31775841, 2019).
prostate carcinoma (2 papers, 2021). A carcinoma that arises from epithelial cells of the prostate gland. "Further multivariate Cox regression analysis was performed to select 6-gene prognostic signature (FADD, GABARAPL2, MYC, RAB24, RUBCN, and NPC1) and calculated the risk score of the prostate cancer patients." (PMID 33402116, 2021).
asthma (1 paper, 2020). "Several genes intersect in asthma phases, in which RAB24 and ADAMTS19 are located in the same branch in a set of moderate-to-severe asthma genes; these genes are linked to immune gene airway diseases and autophagy, suggesting the involvement of these genes in the pathogenesis of asthma." (PMID 32512817, 2020).
COVID-19 (1 paper, 2024). A disease caused by infection with severe acute respiratory syndrome coronavirus 2. "Our work highlighted an increased expression of genes related to the endomembrane system, such as RAB1B, RAB24, RAB32, JAK3, and SELP, in severe COVID-19 patients’ blood samples." (PMID 38262689, 2024).
latent infection (1 paper, 2021). "In another study, also in an Ethiopian cohort of HIV co-infected TB patients, 7 genes (FCGR1A, RAB24, TLR1, TLR4, MMP9, NLRC4, and IL1B) accurately discriminated between active tuberculosis disease and latent infection." (PMID 33692804, 2021).
medullary carcinoma (1 paper, 2021). "In radiation-induced medullary carcinoma in 4W rats, the expression of Cdkn2a and Cxcr4 increased, whereas that of seven autophagy regulatory genes (Dapk1, Eif2ak3, Gaa, Hgs, Mapkl4, Mapt, and Pim2) and five autophagy machinery components (Atg4b, Atg5, Gabarapl2, Rab24, and Wipi1) decreased." (PMID 34580369, 2021).
medulloblastoma (1 paper, 2026). A malignant, invasive embryonal neoplasm arising from the cerebellum. "We also observed elevated RAB24 staining in medulloblastoma and neuroblastoma, two paediatric cancers of neuronal origin." (PMID 41591549, 2026).
nonalcoholic fatty liver disease (1 paper, 2024). "RAB24 is highly upregulated in the livers of obese patients with nonalcoholic fatty liver disease (NAFLD)." (PMID 39883197, 2024).
pancreatic cancer (1 paper, 2022). "The expression levels of BAK1, ITGA3, BAG3, and APOL1 were statistically increased in pancreatic cancer samples versus normal samples, while those of RAB24 was decreased." (PMID 35488119, 2022). "Using univariate Cox regression, a forest map was generated showing seven ARGs associated with pancreatic cancer prognosis: BAK1, ITGA3, BIRC5, WDR45, BAG3, APOL1, and RAB24." (PMID 35488119, 2022). "BAK1, ITGA3, BAG3 and APOL1 were highly expressed in most pancreatic cancer and pancreatic ductal adenocarcinoma cell lines, while RAB24 was poorly expressed." (PMID 35488119, 2022). "Compared with those from the normal controls, immunohistochemical results from the pancreatic tissues revealed statistical increases in the expression of BAK1, ITGA3, BAG3, and APOL1 in pancreatic cancer patients; no immunohistochemical data were available for RAB24." (PMID 35488119, 2022).
cancer (5 papers, 2014 to 2026). A tumor composed of atypical neoplastic, often pleomorphic cells that invade other tissues. "The observed differences in RAB24 levels between cancer types and between malignant and normal tissues, suggest that RAB24 may serve as a potential diagnostic or differentiation marker in specific tumour types." (PMID 41591549, 2026). "Collectively, our findings provide a comprehensive overview of RAB24 protein levels across mouse tissues and a wide spectrum of human cancers." (PMID 41591549, 2026). "RAB24 staining in cancers of the breast and skin was higher than in the corresponding normal tissues, while it was reduced in cancers of the digestive system and the urinary tract." (PMID 41591549, 2026). "We further analysed immunohistochemical staining for RAB24 in human cancers and normal tissues." (PMID 41591549, 2026). "Some Rabs, such as Rab1b, Rab4b, Rab10, Rab22a, Rab24, and Rab25, are dysregulated in many cancers." (PMID 24587032, 2014).
tumor (2 papers, 2017 to 2026). "The silencing of miR-615-5p relieves the suppression of RAB24 and results in tumor growth, metastasis and VM." (PMID 27487123, 2017). "Thus, miR-615-5p, who is downregulated by KDM4B-mediated hypermethylation in its promoter, functions as a tumor suppressor by inhibiting RAB24 expression in HCC." (PMID 27487123, 2017).
RAB24 also shares sentences with these, for which no sentence is quoted: cerebellar ataxia (3 papers); cardiovascular disease (1); cholelithiasis (1); coinfection (1); degenerative joint diseases (1); Hepatic steatosis (1); infection (1); Juvenile onset (1); metastatic tumors (1); neuroblastoma (1); neurodegenerative disease (1); pancreatic ductal adenocarcinoma (1); prostate tumor (1); tuberculosis (1).